VPS13A (vacuolar protein sorting 13 homolog A)
Description:
Mediates the transfer of lipids between membranes at organelle contact sites (By similarity). Binds phospholipids. Required for the formation or stabilization of ER-mitochondria contact sites which enable transfer of lipids between the ER and mitochondria. Negatively regulates lipid droplet size and motility. Required for efficient lysosomal protein degradation.
Synonyms: CHAC; KIAA0986; BLTP5A; CHOREIN
Tractability: Antibody: UniProt places it where antibodies can reach, with high confidence. PROTAC: ubiquitination databases record sites on it; its protein half-life has been measured.
Gene: Protein-coding gene on chromosome 9 (77,177,445 to 77,421,537, forward strand). Ensembl gene ENSG00000197969.
Subcellular location: Mitochondrion outer membrane; Endoplasmic reticulum membrane; Endosome membrane; Lysosome membrane; Lipid droplet; Golgi apparatus; Cytoplasmic vesicle, secretory vesicle, neuronal dense core vesicle
Subcellular location (Human Protein Atlas): Mitochondria
Gene Ontology:
Molecular function: protein binding; phospholipid transfer activity
Biological process: autophagy; lysosomal protein catabolic process; Golgi to endosome transport; intermembrane lipid transfer; intracellular protein localization; macroautophagy; mitochondrion organization; phospholipid transport
Cellular component: endoplasmic reticulum membrane; endosome membrane; lipid droplet; lysosomal membrane; mitochondria-associated endoplasmic reticulum membrane contact site; mitochondrial membrane; mitochondrial outer membrane; mitochondrion; Golgi apparatus; neuronal dense core vesicle lumen; cytosol; dense core granule; endoplasmic reticulum; neuron projection; neuronal cell body; neuronal dense core vesicle; sperm midpiece
Genetic constraint (gnomAD): Loss-of-function variants: 188 observed, 305.01 expected, observed/expected ratio (o/e) 0.62, 90% interval 0.55 to 0.7. The upper end of that interval is the gene's LOEUF score, 0.7, which puts it in group 2 of 6, group 1 being the genes least tolerant of losing a copy. Missense variants: 3,010 observed, 3,428.6 expected, observed/expected ratio (o/e) 0.88, 90% interval 0.85 to 0.9. Synonymous variants: 1,082 observed, 1,140.7 expected, observed/expected ratio (o/e) 0.95, 90% interval 0.9 to 1.
Homologues: Orthologues: chimpanzee VPS13A (99% identical), macaque VPS13A (97% identical), rabbit VPS13A (89% identical), dog VPS13A (89% identical), pig VPS13A (87% identical), mouse Vps13a (84% identical), guinea pig VPS13A (82% identical), rat Vps13a (79% identical), tropical clawed frog vps13a (62% identical), zebrafish vps13a (57% identical), Drosophila melanogaster Vps13 (30% identical), Caenorhabditis elegans vps-13 (29% identical). Paralogues in human: VPS13C (43% identical), VPS13D (19% identical).
Diseases named in the same sentence as VPS13A in open-access papers:
VPS13A is named in the same sentence as 51 diseases in open-access papers, as found by Europe PMC text mining. Sharing a sentence is not in itself a finding about the gene and the disease. The quoted sentences say what the papers report.
chorea-acanthocytosis (63 papers, 2012 to 2026). Chorea-acanthocytosis (ChAc) is a form of neuroacanthocytosis and is characterized clinically by a Huntington disease-like phenotype with progressive neurological symptoms including movement disorders, psychiatric manifestations and cognitive disturbances. "VPS13A disease (formerly chorea-acanthocytosis; due to bi-allelic variants in VPS13A) and XK disease (formerly McLeod syndrome; due to variants of XK) are rare neurodegenerative diseases, classified together as the “neuroacanthocytosis syndromes”." (PMID 41522673, 2026). "VPS13A disease (chorea-acanthocytosis; ChAc) is caused by loss-of-function mutations in the gene encoding the lipid-transfer protein VPS13A." (PMID 41522673, 2026). "Loss of the VPS13A protein resulting from mutations in the VPS13A gene cause VPS13A disease/chorea-acanthocytosis." (PMID 41522673, 2026). "VPS13A is an intermembrane lipid-transfer protein whose loss-of-function mutations, causing the protein depletion, lead to chorea-acanthocytosis (ChAc), an ultra-rare autosomal recessive neurodegenerative disorder." (PMID 41522673, 2026). "VPS13A disease (chorea‐acanthocytosis) is a rare neurodegenerative disorder caused by biallelic variants in VPS13A, typically presenting with hyperkinetic movement disorders, while neuromuscular signs are often mild." (PMID 41030128, 2026). "VPS13A mutations cause chorea-acanthocytosis (VPS13A disease), a Huntington’s like condition due to degeneration of the caudate nucleus of the brain and abnormal red blood morphology." (PMID 40956846, 2025). "Chorea-acanthocytosis (ChAc)/VPS13A disease is an ultra-rare, highly invalidating disease due to mutations in the VPS13A gene, encoding for chorein." (PMID 37928888, 2023). "Loss of function mutations in the VPS13A gene cause VPS13A disease/ chorea-acanthocytosis, a neurodegenerative disorder of the young adulthood." (PMID 37928888, 2023). "Chorea-acanthocytosis and McLeod syndrome are due to mutations in VPS13A and XK, respectively, but share similar clinical manifestations: movement disorders due to degeneration of the caudate nucleus and acanthocytes, i.e. spiculated red blood cells (RBCs)." (PMID 37928888, 2023). "Mutations in the corresponding genes cause different neurological diseases: Chorea-acanthocytosis, recently renamed as VPS13A disease (VPS13A), Cohen syndrome (VPS13B), Parkinson’s disease (VPS13C), and spastic ataxia (VPS13D)." (PMID 36977596, 2023). "The NAS spectrum includes the neurodegenerative disorders chorea-acanthocytosis (VPS13A disease) and McLeod syndrome (XK disease) caused by gene mutations in VPS13A and XK, respectively." (PMID 37928888, 2023). "Chorea-acanthocytosis (ChAc) is a rare neurodegenerative disorder that is caused by pathogenic variants of the Vacuolar Protein Sorting 13 homolog A (VPS13A) gene, which is located on chromosome 9q21 and follows an autosomal recessive inheritance pattern." (PMID 37794323, 2023). "VPS13A disease (formerly chorea-acanthocytosis; due to bi-allelic mutations in VPS13A) and XK disease (formerly McLeod syndrome; due to mutations of XK) are rare neurodegenerative diseases, classified together as the “neuroacanthocytosis syndromes”." (PMID 37928888, 2023). "Mutations in the VPS13A gene, which result in chorea acanthocytosis, cause a number of changes in cells at the molecular level." (PMID 37928888, 2023). "Chorea acanthocytosis (ChAc) is an autosomal-recessive neurodegenerative disorder caused by mutations in the gene encoding vacuolar protein sorting factor 13A (VPS13A)." (PMID 37928888, 2023). "Choreoacanthocytosis, one of the forms of neuroacanthocytosis, is caused by mutations in vacuolar protein sorting-associated protein A (VPS13A), and is often misdiagnosed with other form of neuroacanthocytosis with discrete genetic defects." (PMID 37209156, 2023).
chorea-acanthocytosis (continued). "The importance of ubiquitously expressed VPS13A protein in the organism is evident by the impact of mutations on major hematological and neurological functional loss leading to choreoacanthocytosis." (PMID 37209156, 2023). "Chorea-acanthocytosis and McLeod syndrome, due to mutations in VPS13A and XK, respectively, share similar manifestations: jerking movements due to degeneration of the caudate nucleus and star-shaped erythrocytes." (PMID 35994651, 2022). "Mutations in VPS13A result in chorea-acanthocytosis (ChAc), an ultrarare neurodegenerative disease affecting less than 1–5 individuals per 1 million." (PMID 35563497, 2022). "Supporting the idea that VPS13A and XK collaborate, mutations in either one give rise to similar disease phenotypes (chorea-acanthocytosis and McLeod syndrome, respectively; Park and Neiman, 2020)." (PMID 35267021, 2022). "Chorea-Acanthocytosis (ChAc), a rare autosomal recessive inherited neurological disorder, originated from variants in Vacuolar Protein Sorting 13 homolog A (VPS13A) gene." (PMID 33679298, 2021). "We have introduced mutations in the yeast VPS13 based on alleles found in chorea-acanthocytosis (VPS13A), Cohen syndrome (VPS13B), FTLD (VPS13C), and cerebellar ataxia (VPS13D) patients." (PMID 34046249, 2021). "In 2001 loss-of-function mutations in a human gene (now called VPS13A) with strong similarities to yeast VPS13 were shown to cause a very rare neurodegenerative disease called chorea-acanthocytosis." (PMID 34216812, 2021). "Homozygous null mutations in VPS13A result in chorea-acanthocytosis, an age-dependent Huntington chorea-like neurodegenerative disease characterized by progressive loss of movement control and cognitive functions (hence the name Chorein for VPS13A)." (PMID 34216812, 2021). "Chorea-Acanthocytosis (ChAc) is an ultra-rare neurodegenerative disease caused by mutations in the VPS13A gene." (PMID 34046249, 2021). "VPS13A is a lipid transfer protein that localizes to different membrane contact sites between organelles and its mutation causes the rare disease chorea-acanthocytosis (ChAc)." (PMID 34046249, 2021). "Mutations in the VPS13A and XK genes cause chorea-acanthocytosis (ChAc) and McLeod syndrome, respectively." (PMID 34046249, 2021). "Strikingly, mutations in the genes encoding the 4 homologous VPS13 proteins are associated with distinct neurological disorders: chorea-acanthocytosis (VPS13A), Cohen syndrome (VPS13B), early onset Parkinson’s disease (VPS13C) and ataxia (VPS13D)." (PMID 33809364, 2021). "Chorea-Acanthocytosis (ChAc) is a devastating, little understood, and currently untreatable neurodegenerative disease caused by VPS13A mutations." (PMID 34046249, 2021). "Recessive variants in VPS13A induce chorea acanthocytosis and in VPS13C early onset Parkinson disease." (PMID 33426505, 2020). "Chorea-acanthocytosis is an autosomal recessive disease caused by mutations in the VPS13A gene, which encodes the protein chorein." (PMID 28515033, 2018). "In humans, mutations in the gene encoding the family member VPS13A lead to the neurodegenerative disorder chorea-acanthocytosis." (PMID 25915401, 2015). "Chorein encoded by VPS13A (vacuolar protein sorting-associated protein 13A) is defective in chorea-acanthocytosis." (PMID 25871399, 2015). "Mutations in the VPS13A gene result in either the absence or significantly reduced expression of the protein in all tissues, including RBCs, in patients with Chorea acanthocytosis, where loss of VPS13A function not only contributes to neurological symptoms but also leads to abnormal RBC morphology." (PMID 40016214, 2025). "Chorea-acanthocytosis has been associated with loss-of-function variants in the VPS13A gene." (PMID 40799282, 2025). "Moreover, Vps13a mutations lead to chorea-acanthocytosis, a rare disorder that also affects the brain and reduced chorein levels have been linked to Alzheimer’s disease." (PMID 38217668, 2024).
chorea-acanthocytosis (continued). "Mutations in the VPS13A gene are implicated in the pathogenesis of chorea-acanthocytosis (ChAc), a rare autosomal recessive neurodegenerative disorder characterized by chorea, orofacial dyskinesias, hyperkinetic movements, seizures, cognitive impairment, and acanthocytosis." (PMID 39063018, 2024). "Interestingly, loss-of-function mutations in VPS13A are known to cause chorea-acanthocytosis (ChAc), an autosomal recessive neurodegenerative disorder." (PMID 39099167, 2024). "Interestingly, a VPS13A chorea-acanthocytosis mutation causing amino acid substitution in the APT1 domain enhanced interactions with phosphatidylinositol (PI)-rich liposomes in the presence of calcium ions." (PMID 33809364, 2021). "The VPS13A gene is associated with the neurodegenerative disorder Chorea Acanthocytosis." (PMID 30741634, 2019). "Mutations in VPS13A and XK are associated with chorea-acanthocytosis (ChAc) and Mcleod (MLS) syndromes respectively." (PMID 41522673, 2026). "Chorea-acanthocytosis (ChAc) is the most common subtype of neuroacanthocytosis (NA) caused by mutations in VPS13A (vacuole protein sorting-associated protein 13A)." (PMID 40917663, 2025). "VPS13A, also known as chorein, whose loss of function causes chorea-acanthocytosis (ChAc), is characterized by Huntington’s-disease-like neurodegeneration and neuropsychiatric symptoms in addition to acanthocytosis in red blood cells." (PMID 38275411, 2024). "Chorea-acanthocytosis (ChAc) is an extremely rare autosomal recessive neurodegenerative disorder caused by mutations in VPS13A, which is located on 9q21, and is a subtype of neuroacanthocytosis syndrome." (PMID 39119561, 2024). "Chorea-acanthocytosis (ChAc) is a rare, neurodegenerative disorder caused by mutations in the VPS13A gene." (PMID 39119561, 2024). "Chorea-acanthocytosis (ChAc) is a rare hereditary autosomal recessive neurodegenerative disorder caused by pathogenic variants of the Vacuolar Protein Sorting 13 homolog A (VPS13A) gene." (PMID 37794323, 2023). "Chorea-acanthocytosis (ChAc) is a rare genetic disease caused by loss-of-function-mutation of the vacuolar protein sorting-associated protein 13A (VPS13A) which is an encoding gene of the protein chorein." (PMID 35130982, 2022). "Chorea-acanthocytosis (ChAc) and McLeod syndrome are diseases with shared clinical manifestations caused by mutations in VPS13A and XK, respectively." (PMID 35994651, 2022). "Chorea-acanthocytosis (ChAc) is a rare hereditary autosomal recessive neurodegenerative disease, caused by mutations in the VPS13A gene." (PMID 34066168, 2021). "Twenty years ago, it was discovered a conserved sorting-associated protein (VPS13A) that was mutant in chorea-acanthocytosis (ChAc)." (PMID 34046249, 2021). "There are four human homologs (VPS13A–D), and mutations in these genes result in chorea-acanthocytosis (ChAc) (VPS13A), Cohen’s syndrome (VPS13B), early-onset parkinsonism (VPS13C) and childhood-onset movement disorder (VPS13D)." (PMID 33668157, 2021). "Chorea-acanthocytosis (ChAc) is a rare neurodegenerative disease associated with mutations in the human VPS13A gene." (PMID 30635263, 2019). "Mutations in VPS13A lead to a rare, fatal neurodegenerative disease: chorea-acanthocytosis (ChAc; OMIM 200150)." (PMID 30635263, 2019). "Chorea-acanthocytosis (ChAc) relates to mutations in VPS13A, McLeod Syndrome (MLS) has mutations in XK, Huntington’s Disease-like 2 (HDL2) in JPH3, and panthotenate kinase-associated neurodegeneration (PKAN) in PANK2." (PMID 24098554, 2013). "Chorea-acanthocytosis (ChAc) is an autosomal recessive disease due to mutations of the VPS13A gene encoding for chorein." (PMID 24223913, 2013). "VPS13A disease (previously known as chorea-acanthocytosis), is an ultra-rare autosomal recessive neurodegenerative disorder caused by mutations of the VPS13A gene encoding VPS13A protein, known also as chorein." (PMID 41522673, 2026).
chorea-acanthocytosis (continued). "VPS13A disease, formerly referred to as chorea‐acanthocytosis, is an autosomal recessive disorder due to biallelic variants in VPS13A, which encodes for VPS13A (chorein)." (PMID 41030128, 2026). "The core neuroacanthocytosis syndromes, i.e., chorea-acanthocytosis/VPS13A disease (ChAc) and McLeod syndrome/XK disease (MLS), are respectively due to mutations in VPS13A and XK genes and share similar manifestations including the formation of acanthocytes." (PMID 40213144, 2025). "VPS13A and VPS13C are bridge-like lipid transport proteins with distinct subcellular localization and function, and their absence is linked with chorea-acanthocytosis and Parkinson's disease, respectively." (PMID 40956846, 2025). "McLeod syndrome (MLS or XK disease) and VPS13A disease (formerly chorea‐acanthocytosis; ChAc) are the core syndromes of this group." (PMID 40898647, 2025). "Recent evidence suggests XK forming a complex with chorein/VPS13A, a likely hint for shared pathophysiological mechanisms in clinical resemblance of MLS and VPS13A disease (chorea acanthocytosis)." (PMID 39233738, 2024). "VPS13A disease (also known as Chorea-Acanthocytosis, ChAc) is a representative subtype of the neuroacanthocytosis (NA) syndromes, characterized by neurodegeneration in the central nervous system and acanthocytosis in peripheral blood." (PMID 39659962, 2024). "In humans, loss‐of‐function mutations in the Vacuolar Protein Sorting 13 Homolog A (VPS13A) gene, which encodes a large protein named chorein, cause chorea‐acanthocytosis (ChAc)." (PMID 39514409, 2024). "Neuroacanthocytosis syndromes (NAS) refer to a group of inherited neurodegenerative disorders, including VPS13A disease (chorea-acanthocytosis) and XK disease (McLeod syndrome)." (PMID 37928888, 2023). "VPS13A is a lipid transfer protein localized at different membrane contact sites between organelles, and mutations in the corresponding gene produce a rare neurodegenerative disease called chorea‐acanthocytosis (ChAc), also known as VPS13A disease." (PMID 37163371, 2023). "Loss of functionmutations in VPS13A and VPS13C cause chorea acanthocytosis and Parkinson'sdisease, respectively." (PMID 36147729, 2022). "As further evidence for a role of VPS13A in autophagy, erythrocytes from chorea-acanthocytosis patients accumulate autophagosomal cargo proteins." (PMID 33809364, 2021). "Loss of function mutations of the chorein-encoding gene VPS13A lead to chorea-acanthocytosis (ChAc), a neurodegenerative disorder with accelerated suicidal neuronal cell death, which could be reversed by lithium." (PMID 32439941, 2020). "It has been reported that the mutations of VPS13A (OMIM *605978), VPS13B (OMIM *607817), and VPS13C (OMIM *608879) lead to chorea acanthocytosis (OMIM #200150), Cohen syndrome (OMIM #216550), and parkinsonism (OMIM #616840), respectively." (PMID 31876103, 2020). "Alterations of vacuolar protein sorting‐associated protein 13 (VPS13) family members including VPS13A, VPS13B, and VPS13C lead to chorea acanthocytosis, Cohen syndrome, and parkinsonism, respectively." (PMID 31876103, 2020). "Mutations in VPS13A and VPS13B cause the genetic diseases chorea-acanthocytosis (ChAc) and Cohen syndrome, respectively, and a loss of VPS13C function has recently been linked to early-onset Parkinson's disease." (PMID 27329800, 2016). "The availability of molecular genetic testing has critically influenced the approach to diagnosing rare and ultrarare conditions such as VPS13A disease and XK disease (previously known as chorea-acanthocytosis and McLeod syndrome, respectively) as well as Cohen syndrome (due to VPS13B mutations)." (PMID 41522673, 2026). "VPS13A (Vacuolar protein sorting 13 homolog A) disease (previously known as Chorea-acanthocytosis, ChAc; OMIM #200150), is the most common subtype of neuroacanthocytosis syndrome, characterized by the presence of abnormal star-shaped red blood cells (acanthocytes) and neurological disturbances." (PMID 41373679, 2025).